CYP24A1 (cytochrome P450 family 24 subfamily A member 1)
Description:
A cytochrome P450 monooxygenase with a key role in vitamin D catabolism and calcium homeostasis. Via C24- and C23-oxidation pathways, catalyzes the inactivation of both the vitamin D precursor calcidiol (25-hydroxyvitamin D(3)) and the active hormone calcitriol (1-alpha,25-dihydroxyvitamin D(3)). With initial hydroxylation at C-24 (via C24-oxidation pathway), performs a sequential 6-step oxidation of calcitriol leading to the formation of the biliary metabolite calcitroic acid. With initial hydroxylation at C-23 (via C23-oxidation pathway), catalyzes sequential oxidation of calcidiol leading to the formation of 25(OH)D3-26,23-lactone as end product. Preferentially hydroxylates at C-25 other vitamin D active metabolites, such as CYP11A1-derived secosteroids 20S-hydroxycholecalciferol and 20S,23-dihydroxycholecalciferol. Mechanistically, uses molecular oxygen inserting one oxygen atom into a substrate, and reducing the second into a water molecule, with two electrons provided by NADPH via FDXR/adrenodoxin reductase and FDX1/adrenodoxin.
Synonyms: CYP24; CP24; P450-CC24; lncBCAS1-4_1; HCAI; HCINF1
Tractability: Small molecule: a high-quality ligand is known; it belongs to a druggable protein family. PROTAC: ubiquitination databases record sites on it; a small molecule that binds it is known.
Target class: Cytochrome P450 family 24; Enzyme; Cytochrome P450 family 24A; Cytochrome P450; Cytochrome P450 24A1
Safety:
Unwanted effects reported when the protein is acted on. In parentheses: how it was acted on, where the effect was seen, and who reports it.
nephrotoxicity (source: ClinPGx)
Gene: Protein-coding gene on chromosome 20 (54,153,446 to 54,173,986, reverse strand). Ensembl gene ENSG00000019186.
Subcellular location: Mitochondrion
Subcellular location (Human Protein Atlas): Mitochondria
Pathways (Reactome):
Metabolism: Vitamin D (calciferol) metabolism; Vitamins
Disease: Defective CYP24A1 causes HCAI
Gene Ontology:
Molecular function: 1-alpha,25-dihydroxyvitamin D3 23-hydroxylase activity; 1-alpha,25-dihydroxyvitamin D3 24-hydroxylase activity; 25-hydroxycholecalciferol-23-hydroxylase activity; 25-hydroxycholecalciferol-24-hydroxylase activity; vitamin D3 25-hydroxylase activity; heme binding; iron ion binding; monooxygenase activity; oxidoreductase activity, acting on paired donors, with incorporation or reduction of molecular oxygen; vitamin D 24-hydroxylase activity
Biological process: osteoblast differentiation; response to vitamin D; vitamin D catabolic process; vitamin D metabolic process; vitamin D receptor signaling pathway; vitamin metabolic process; calcitriol biosynthetic process from calciol; cellular response to vitamin D; lipid biosynthetic process; steroid metabolic process
Cellular component: mitochondrion; mitochondrial inner membrane
Genetic constraint (gnomAD): Loss-of-function variants: 44 observed, 37.55 expected, observed/expected ratio (o/e) 1.17, 90% interval 0.92 to 1.51. The upper end of that interval is the gene's LOEUF score, 1.51, which puts it in group 6 of 6, group 1 being the genes least tolerant of losing a copy. Missense variants: 456 observed, 394.34 expected, observed/expected ratio (o/e) 1.16, 90% interval 1.07 to 1.25. Synonymous variants: 146 observed, 150.06 expected, observed/expected ratio (o/e) 0.97, 90% interval 0.85 to 1.12.
Homologues: Orthologues: macaque CYP24A1 (98% identical), dog CYP24A1 (89% identical), pig CYP24A1 (88% identical), rabbit CYP24A1 (87% identical), chimpanzee CYP24A1 (86% identical), rat Cyp24a1 (83% identical), mouse Cyp24a1 (83% identical), guinea pig CYP24A1 (80% identical), tropical clawed frog cyp24a1 (68% identical), zebrafish cyp24a1 (64% identical), Drosophila melanogaster sad (25% identical). Paralogues in human: CYP27C1 (31% identical), CYP27A1 (30% identical), CYP27B1 (30% identical).
Diseases named in the same sentence as CYP24A1 in open-access papers:
CYP24A1 is named in the same sentence as 252 diseases in open-access papers, as found by Europe PMC text mining. Sharing a sentence is not in itself a finding about the gene and the disease. The quoted sentences say what the papers report.
Hypercalcemia (86 papers, 2013 to 2026). An abnormally increased calcium concentration in the blood. "Pregnancy increases the risk of hypercalcemia in individuals with a CYP24A1 mutation by a physiologic increase of 1-α-hydroxylase." (PMID 41635392, 2026). "Loss-of-function mutations in CYP24A1 were first identified in infants with idiopathic infantile hypercalcemia and have since been recognized to cause a spectrum of symptoms across all age groups." (PMID 41377203, 2025). "Patients with biallelic CYP24A1 mutations present a PTH-independent hypercalcemia highly variable in its severity, but generally mild outside the settings of early infancy and pregnancy." (PMID 40565034, 2025). "The management of hypercalcemia due to CYP24A1 pathogenic variants includes calcium and vitamin D restriction as well as hydration." (PMID 40765620, 2025). "There was also a recent report of successful treatment of 1,25(OH)2D-mediated hypercalcemia due to pathogenic CYP24A1 variants with cinacalcet." (PMID 40765620, 2025). "While pHPT is surgically curable, CYP24A1 mutation-associated hypercalcemia requires conservative management." (PMID 41009532, 2025). "The CYP24A1 defects cause hypercalcemia by directly blocking degradation of 1,25-(OH)2D3, which results in accumulation of active forms of vitamin D3 and enhancement of intestinal calcium absorption and bone reabsorption." (PMID 40943461, 2025). "The initial targeted NGS (next generation sequencing) panel included two genes implicated in idiopathic infantile hypercalcemia and phosphate–vitamin D metabolism: CYP24A1 and SLC34A1." (PMID 41303235, 2025). "We describe 4 young women and 1 man with calcitriol-associated hypercalcemia in whom pathogenic CYP24A1 variants were found to be the cause." (PMID 40765620, 2025). "Clinical clues to the diagnosis of pathogenic variants of CYP24A1 in the setting of calcitriol-induced hypercalcemia are young age, family history, and nephrocalcinosis." (PMID 40765620, 2025). "A rare cause of hypercalcemia is loss-of-function mutations in CYP24A1, which encodes 24-hydroxylase, responsible for the inactivation of active vitamin D metabolites." (PMID 41377203, 2025). "Another pharmaceutical therapeutic option is the enzymatic induction of CYP3A4 by rifampicin, which has been successfully used in patients with CYP24A1 mutations to diminish hypercalcemia and hypercalciuria." (PMID 41009532, 2025). "In conclusion, the diagnosis of CYP24A1 variants requires a high index of suspicion in patients with unexplained calcitriol-induced hypercalcemia." (PMID 40765620, 2025). "This case highlights the diagnostic complexity of persistent hypercalcemia and underscores the importance of also considering rare causes such as CYP24A1 mutations in the differential diagnosis after the exclusion of relevant frequent disease causes." (PMID 41009532, 2025). "This case highlights CYP24A1 mutations as a rare cause of gestational hypercalcemia, unmasked by pregnancy physiology." (PMID 41377203, 2025). "In very rare cases, hypercalcemia can be the result of bi-allelic loss-of-function variants in the CYP24A1 gene." (PMID 40565034, 2025). "Awareness of rare etiologies, such as lactational hypercalcemia and CYP24A1 mutations, can prevent prolonged diagnostic delays and guide appropriate therapeutic strategies." (PMID 41487858, 2025). "We share 5 cases of a rare condition and further broaden the presentation of CYP24A1 variants to not only include worsening hypercalcemia in pregnancy, but also during lactation." (PMID 40765620, 2025). "We report 5 patients with hypercalcemia in whom pathogenic or likely pathogenic variants of CYP24A1 appear to be the cause." (PMID 40765620, 2025). "Physicians should consider pathogenic CYP24A1 variants in patients with unexplained calcitriol-associated hypercalcemia/hypercalciuria." (PMID 40765620, 2025).
Hypercalcemia (continued). "Among cases of vitamin D-sensitive hypercalcemia in children, a 25(OH)D3:24,25(OH)2D3 ratio > 25 with upregulated alternative metabolism via 3-epi-25(OH)D3 has been described to clinically identify CYP24A1’s loss of function." (PMID 39337491, 2024). "Complete loss-of-function mutations in CYP24A1 cause 1,25D-mediated hypercalcemia with appropriately suppressed PTH." (PMID 39688907, 2024). "In patients with proven CYP24A1 mutations, management should concentrate on eliminating or reducing hypercalcaemia and hypercalciuria." (PMID 38665259, 2024). "Like in patients with CYP24A1 mutations, hypercalcaemia, suppressed PTH and inappropriately high 1,25(OH)2D3 are observed." (PMID 38665259, 2024). "A monoallelic variant of CYP24A1 or SLC34A1 gene contributes to symptomatic hypercalcemia, hypercalciuria and nephrocalcinosis." (PMID 38504242, 2024). "24-Hydroxylase, encoded by the CYP24A1 gene, is a crucial enzyme involved in the catabolism of vitamin D. Loss-of-function mutations in CYP24A1 result in PTH-independent hypercalcaemia with high levels of 1,25(OH)2D3." (PMID 38665259, 2024). "It is known that 1,25(OH)2D3 is elevated during normal pregnancy, which additionally promotes hypercalcaemia in women with disturbed calcitriol catabolism associated with CYP24A1 mutation." (PMID 38665259, 2024). "Vitamin D-mediated hypercalcemia is a known trait of CYP24A1 loss-of-function mutations; however, its presence and genetic variability have still to be determined in large-scale population-based studies." (PMID 39337491, 2024). "A genetic predisposition to the dysregulation of calcitriol metabolism has been exemplified by the biallelic mutational loss of the 24-hydroxylase activity of CYP24A1, resulting in idiopathic infantile hypercalcemia." (PMID 39337491, 2024). "These clinical cases reflect that monoallelic variants in CYP24A1 gene can cause infantile hypercalcemia, but the presence of renal calcification is still controversial." (PMID 38504242, 2024). "We present the cases of two siblings exhibiting hypercalcemia secondary to a CYP24A1 loss-of-function mutation." (PMID 37701149, 2023). "Pathogenic variants of CYP24A1 are associated with hypercalcemia due to disruptions in the ability of 24-hydroxylase to break down 1,25-dihydroxyvitamin D (1,25-DHVD)." (PMID 37909006, 2023). "Possible treatments to manage the risk of hypercalcemia in patients with a CYP24A1 loss-of-function mutation include avoidance of vitamin D oversupplementation and excessive sun exposure." (PMID 37701149, 2023). "In summary, we report a case where a patient with severe symptomatic hypercalcemia was found to have primary hyperparathyroidism exacerbated by an underlying heterozygous pathogenic variant in CYP24A1." (PMID 37909006, 2023). "The critical role of CYP24A1 in the catabolism of 1,25(OH)2D3 in humans was noted in studies of very young children and adults with inactivating mutations in CYP24A1 who presented with hypercalcemia and hypercalciuria." (PMID 37408241, 2023). "Measurement of 1,25(OH)2D is helpful in the investigation of patients with unexplained hypercalcaemia, sarcoidosis, granulomatous disorders, pseudo-vitamin D deficiency, rickets, tumour-induced osteomalacia, hyperparatiroidism, and CYP24A1 deficiency." (PMID 35238975, 2023). "Of note, the term idiopathic infantile hypercalcemia is meanwhile considered a misnomer for patients with pathogenic mutations of CYP24A1 as these patients can develop hypercalcemia across their whole life-span." (PMID 35745247, 2022). "A homozygous mutation of the CYP24A1 gene was detected in one patient and facilitated a diagnosis of infantile hypercalcaemia." (PMID 35612621, 2022). "One newborn was compound heterozygous for pathogenic CYP24A1 mutations and developed symptomatic hypercalcemia after receiving 50,000 IU of vitamin D2 on day 1 of his life." (PMID 35745247, 2022).
Hypercalcemia (continued). "Pregnant women with pathogenic CYP24A1 mutations are at particular high risk of hypercalcemia and therewith associated complications." (PMID 35745247, 2022). "A literature review in PubMed using the search terms “CYP24A1” and “pregnancy” was performed on 13 April 2022 to identify articles presenting data on pregnant women with pathogenic CYP24A1 mutations causing hypercalcemia." (PMID 35745247, 2022). "In this work, we present the case of a pregnant woman with hypercalcemia due to pathogenic mutations in CYP24A1." (PMID 35745247, 2022). "Pathogenic mutations of CYP24A1 lead to an impaired catabolism of vitamin D metabolites and should be considered in the differential diagnosis of hypercalcemia with low parathyroid hormone concentrations." (PMID 35745247, 2022). "This is the first report of uniparental disomy of chromosome 20 revealed by infantile hypercalcemia related to CYP24A1 biallelic homozygous variants, underlying the importance of controlling allelic segregation in cases of homozygosity." (PMID 33952337, 2021). "Measurements of 24,25(OH)2D3 have been used in studies of chronic kidney disease, and to determine mutations of CYP24A1 along with idiopathic infantile hypercalcaemia resulting from mutation in CYP24A1." (PMID 34013677, 2021). "In humans, CYP24A1 dysfunction sometimes causes elevated plasma levels of 1,25(OH)2D3 and is associated with idiopathic infantile hypercalcemia or kidney stones." (PMID 33865853, 2021). "Only one patient (patient 10), with a CYP24A1 mutation, had borderline hypercalcemia, which resolved after minimal dose reduction." (PMID 34858904, 2021). "Recently, rifampicin was demonstrated to reduce hypercalcaemia and effectively control 1,25-dihydroxyvitamin D3 levels in patients with CYP24A1 mutations." (PMID 31935940, 2020). "CYP24A1 mutations were first detected following reports of a small cohort of babies developing adverse effects (including hypercalcemia and nephrocalcinosis) as a result of the public health intervention to routinely supplement formula milk with vitamin D." (PMID 31935940, 2020). "A mutation of the CYP24A1 gene has been reported in a 22-year-old male patient with recurrent nephrolithiasis, nephrocalcinosis, hypercalcemia, low parathyroid hormone levels, hypercalciuria and low bone mass." (PMID 33142950, 2020). "Since CYP24A1 mutations clearly result in a genetic disposition to hypercalcemia, we recommend genetic testing in siblings of IIH patients, so that vitamin-D supplementation can be reconsidered." (PMID 28874334, 2018). "In the first CYP24A1 defect, hypercalcemia is directly caused by impaired degradation of 1,25(OH)2D." (PMID 28470390, 2017). "We and others have shown that patients with familial adult and infantile hypercalcemia, have hypercalciuria and nephrolithiasis that are associated with mutations of the CYP24A1 gene." (PMID 26332888, 2015). "The prevalence of CYP24A1 mutations in the general population is unknown, but may contribute to hypercalcemia, a condition with an estimated prevalence of 1/500 patients in the outpatient setting." (PMID 40565034, 2025). "24-hydroxylase deficiency (or infantile hypercalcemia type 1) is an inherited disease associated with biallelic loss-of-function CYP24A1 mutations lead to impaired inactivation of vitamin D metabolites and characterised hypercalcemia, nephrocalcinosis and/or urolithiasis." (PMID 41640145, 2025). "Genetic variants in CYP24A1 lead to a range of phenotypical and biochemical presentations, including idiopathic infantile hypercalcemia, elevated concentrations of 1,25 dihydroxy vitamin D, adult onset nephrocalcinosis, hypercalciuria, hypercalcemia and nephrolithiasis." (PMID 40917505, 2025). "CYP24A1 mutations disrupt vitamin D metabolism, precipitating hypercalcemia." (PMID 40126616, 2025). "CYP24A1 mutations are a rare but important cause of gestational hypercalcemia." (PMID 41377203, 2025).
Hypercalcemia (continued). "Furthermore, emerging evidence suggests that CYP24A1 mutations, which impair the degradation of active vitamin D metabolites, can predispose individuals to hypercalcemia during pregnancy and lactation." (PMID 41487858, 2025). "In addition, recent studies have identified CYP24A1 gene mutations as an emerging cause of pregnancy- and lactation-associated hypercalcemia." (PMID 41487858, 2025). "Risk mitigation: Monitor hypercalcemia in renal insufficiency or CYP24A1 mutation carriers." (PMID 40821024, 2025). "Recently, pathogenic CYP24A1 variants resulting in inability of the 24-hydroxylase enzyme to deactivate 1,25(OH)2D has been found to be a cause of calcitriol-induced hypercalciuria and hypercalcemia in children and adults." (PMID 40765620, 2025). "As hypercalcemia reappeared, an elevated 25(OH)D3/24,25(OH)2D3 ratio and consequently a novel combination of two pathogenic heterozygous missense mutations (c.1186C>T and c.628T>C) of the CYP24A1 gene were found." (PMID 41009532, 2025). "However, there is a report of successful rifampin treatment of hypercalcemia due to pathogenic CYP24A1 variants in a 10-mo-old child." (PMID 40765620, 2025). "Additionally, successful treatment of severe hypercalcemia of infancy due to CYP24A1 variants with pamidronate has been reported." (PMID 40765620, 2025). "Most patients with hypercalcemia due to pathogenic variants of CYP24A1 have biallelic mutations; however, heterozygous variants may cause hypercalciuria and kidney stones and sometimes hypercalcemia." (PMID 40765620, 2025). "Further, because heterozygous individuals may manifest hypercalciuria and hypercalcemia, genetic and biochemical testing of offspring of affected parents, especially those who carry biallelic CYP24A1 variants is advised." (PMID 40765620, 2025). "There may be childhood presentations, especially with biallelic variants in CYP24A1 leading to idiopathic infantile hypercalcaemia, which can lead to death." (PMID 40917505, 2025). "Here, our patient 1 with monoallelic CYP24A1 variant presented symptomatic hypercalcemia in infancy, providing a clinical reference for the view of the potential risk of developing hypercalcemia and related clinical manifestations if exposed to triggering factors." (PMID 38504242, 2024). "CYP24A1 can be stimulated hormonally, and its mutation results in hypercalcemia in pregnancy." (PMID 38791485, 2024). "In the present study, we hypothesized that Cyp24a1 ablation would cause increased serum calcitriol, hypercalcemia, and altered placental mineral transport." (PMID 38577520, 2024). "We hypothesized that loss of Cyp24a1 in fetal mice will cause high calcitriol, hypercalcemia, and increased placental calcium transport." (PMID 38577520, 2024). "Mutations or deletions in CYP24A1 are associated with hypercalcemia and hypercalciuria." (PMID 37414755, 2023). "It is therefore conceivable that chronically elevated concentrations of 1,25(OH)2D in carriers of biallelic pathogenic variants of CYP24A1 may lead to depletion of calcium from bone thereby leading to osteopenia and maintenance of the hypercalcemia." (PMID 36990163, 2023). "This may in turn suppress PTH in the fetus and may explain why newborns of mothers with CYP24A1 mutations are at risk of both, hypercalcemia due to transfer of calcium from the mother during pregnancy and of hypocalcemia due to suppression of PTH." (PMID 35745247, 2022). "Other causes of hypercalcemia, such as genetic mutations of CYP24A1, etc., are extremely rare." (PMID 35889955, 2022). "Intravenous hydration has been used as a treatment approach for several women with pathogenic CYP24A1 mutations during pregnancy and postpartum, but although this treatment is generally safe and efficient for treatment of hypercalcemia, risk of volume overload (edema) should be kept in mind." (PMID 35745247, 2022).